TEAD4 (TEA domain transcription factor 4)
Diseases named in the same sentence as TEAD4 in open-access papers (continued):
Sharing a sentence is not in itself a finding about the gene and the disease.
tumor (continued). "Moreover, genes whose abnormal splicing was negatively correlated to SNORA7A expression were downstream targets of transcription factors such as the tumor angiogenesis regulator HIF1A, the Hippo pathway transcription factor TEAD4 and the tumorigenic transcription factor NF-KB1." (PMID 33519915, 2020). "Finally, TEAD4 overexpression in HCC1937 significantly promotes DNA synthesis and tumor growth." (PMID 25970772, 2015). "Indeed, several of the identified genes in our study are reported to be involved in angiogenesis, tumor angiogenesis and arteriogenesis, i.e. IL-8, ET-1, CARP, HPTPη, ID1, MGSA, SMAD7, HO-1, RHOB, PTHLH, SERPINH1/HSP47, JAG1, GNA13 and TEAD4." (PMID 16594992, 2006). "Finally, miR‐6839‐3p transfection restrained tumour metastasis without affecting proliferation of LAD cells, which was quite similar to the phenotypes of TEAD4 knockdown cells." (PMID 29667772, 2018).
cancer (77 papers, 2016 to 2025). A tumor composed of atypical neoplastic, often pleomorphic cells that invade other tissues. "TEAD1 and TEAD4 were specifically recognised and targeted, with both TEAD1 and TEAD4 implicated in the progression and development of various cancers." (PMID 40744733, 2025). "Among the four TEAD members, the elevated TEAD4 expression is the most frequently observed in various types of cancers and highly associated with clinical significance, such as cancer progression or patient’s survival rate." (PMID 35602596, 2022). "Activated YAP associates with enhancer loci via TEAD4-DNA-binding protein and stimulates cancer aggressiveness." (PMID 33514403, 2021). "Below, we will focus on IKAROS and TEAD4 as TFs well representing how AS variants devoid of a functional DBD impact on cancer hallmarks." (PMID 32244895, 2020). "Several lines with evidence have revealed that TEAD4 has oncogenic roles and prognostic significance underlying multiple cancer contexts." (PMID 30459528, 2018). "Similarly, NFE2 and TEAD4 are also implicated in various types of cancers and are strongly associated with clinical significance." (PMID 38501838, 2024). "There are also studies showing that as an anti-cancer factor, miR-1343-3p can inhibit the expression and activation of the GC oncogene TEA domain transcription factor 4 (TEAD4)." (PMID 40978035, 2025). "Strikingly, we also demonstrated that the driving of TEAD4 into the condensate state by VGLL4/RFXANK or an engineered peptide significantly limited cancer cell growth and increased apoptosis." (PMID 39358623, 2024). "The data presented indicate that the DNA-methylation status of the TEAD4-ΔN promoter plays a critical role in regulating organ size, cancer development, and placenta differentiation." (PMID 38396900, 2024). "Immunohistochemical analysis data from the human protein atlas revealed a significant upregulation of TEAD3 and TEAD4 in HNSCC cancer tissues." (PMID 39430767, 2024). "According to a Pan‐Cancer investigation of entire genomes, 6% of the 2565 cancer patients analysed had TEAD4 abnormalities." (PMID 38501838, 2024). "A pan-cancer differential TEADs expression identified a high expression of TEAD1, TEAD2, TEAD3, and TEAD4 in 3, 6, 5, and 12 types of cancer tissues, respectively." (PMID 38607003, 2024). "Intriguingly, abundant cancer-associated TFs were identified preferentially binding to ABC variants, for instance, TEAD4 have been extensively reported that plays important roles in gene expression regulation among cancers." (PMID 37749132, 2023). "TEAD4 is an oncogene with important roles in cancer, including epithelial-to-mesenchymal transition (EMT), metastasis, chemotherapeutic drug resistance and, consistently, it represents a valuable target for anticancer treatment." (PMID 36186582, 2022). "Based on Pan-Cancer analysis of whole genomes, 6% of 2,565 cancer patients analyzed in that study possess TEAD4 abnormality (ICGC/TCGA Pan-Cancer Analysis of Whole Genomes Consortium, 2020)." (PMID 35602596, 2022). "Since palmitoylation is so crucial to TEAD4’s activity, its inhibitor currently evaluated for cancer therapy represents another option." (PMID 35602596, 2022). "The underlying mechanism of both YAP-dependent and independent nodules on TEAD4 regulation should further elucidated to improve the cancer treatment." (PMID 35602596, 2022). "Silencing of serum/glucocorticoid regulated kinase 1 (SGK1) disrupts the transcriptional YAP/TEAD4 complex, leading to the suppression of cancer cell growth and migration in vivo and in vitro." (PMID 35602596, 2022). "In coordination with YAP, TAZ, and VGLL, TEAD4 plays a critical role in cancer proliferation, including cell proliferation, metastasis, and cancer stem cell maintenance." (PMID 35969177, 2022). "Among them, TEAD4 plays an important role in cancer, being actively involved in the regulation of metastatic behavior and cancer stem cell dynamics (Barry." (PMID 36186582, 2022).
cancer (continued). "Although TEAD4 plays an essential role in determining that differentiation fate of the blastocyst, it also promotes tumorigenesis by enhancing metastasis, cancer stemness, and drug resistance." (PMID 35602596, 2022). "Based on publicly available ENCODE TEAD4 ChIP-seq datasets (GSM1614035, GSM1010860, GSM1010868, GSM1010772 and GSM1010875), we found that ALOXE3 is a putative YAP-TEAD4 gene target in various cancer cell lines." (PMID 34977009, 2021). "In recent years, the effects of TEAD4 on promoting cancer progression have been gradually concerned." (PMID 33517828, 2021). "Using publicly available TEAD4 ChIP-seq data in cancer cell lines, we found TEAD4-binding sites overlap 6/8 (75%) FMREs identified in HGSOCs, including the 6p22.1 enhancer." (PMID 32332753, 2020). "Collectively, our findings together with others strongly suggest that TEAD4 probably functions as a putative pro-tumorigenic gene via enhancing cancer cell proliferation, migration and invasion in HNSCC." (PMID 30459528, 2018). "Several previous reports have proposed important clinical relevance of TEAD4 overexpression in human cancer." (PMID 30459528, 2018). "Genomic analyses of TCGA data sets indicate that splicing of TEAD4 is commonly altered in cancer patients to reduce TEAD4-S." (PMID 27291620, 2016). "TEAD4, a member of the TEA (Transcriptional enhanced associate) domain-containing transcription factors family including TEAD1, 2, 3, and 4, has been reported to possess oncogenic effects in various cancers." (PMID 39735666, 2025). "Furthermore, previous studies have shown that VGLL1 can directly interact with TEAD1 and TEAD4 in cancer cells." (PMID 38912065, 2024). "According to a report, the short isoform of TEAD4 may impede TEAD4-mediated gene activation in cancer cell lines." (PMID 38396900, 2024). "TEAD4, one of the seven identified TF candidates, has been well studied as a downstream TF of the Hippo signaling pathway and has also been studied as an attractive target for cancer therapy." (PMID 39358623, 2024). "This is consistent with the role of TEAD4 in promoting histone acetylation in cancer cells." (PMID 38233381, 2024). "Finally, they also promote cancer stemness and chemoresistance by activating TEA Domain Transcription Factor 4 (TEAD4) and YAP." (PMID 38831236, 2024). "As a member of the TEAD family, TEAD4 is a putative growth inhibitor involved in various cancers." (PMID 37856006, 2023). "CA3, an inhibitor of YAP/TEAD transcriptional activity, inhibits the proliferation and metastasis of other cancers; however, whether it inhibits PAF1-mediated YAP1/TEAD4 transcriptional activity and cancer stem cells in PC is unknown." (PMID 36180487, 2022). "Here, we explore some of the top ranked TRs including histone deacetylase 2 (HDAC2), estrogen receptor 1 (ESR1), TEA domain family member 4 (TEAD4), achaete-scute homolog 1 (ASCL1), androgen receptor (AR) and yes associated protein 1 (YAP1) in several cancer types." (PMID 33778495, 2021). "TEAD4 is highly expressed in cancer tissue when compared to normal tissue." (PMID 33893278, 2021). "Those patients with recurrent cancer at first year show the highest TEAD4 expression." (PMID 33893278, 2021). "Our study provided a possible cancer-promoting mechanism for TEAD4." (PMID 32637580, 2020). "CEBPB, MEIS3, and TEAD4 were co-expressed with has-miR-5p in cancers." (PMID 32637580, 2020). "Additionally to MEK1 and TEAD4, GSEA analysis also revealed other cancer‐associated gene sets as the significantly enriched signature in the miR‐1271 down‐geneset." (PMID 29862663, 2018). "The TEAD4 gene belongs to the TEAD (transcriptional enhancer factor domain) transcription factors that are required for activating the proliferation genes targeted by Hippo signaling in cancer." (PMID 30102725, 2018). "Moreover, in line with the IHC findings, we found that the mRNA levels of TEAD4 in pre-stored carcinoma samples were significantly upregulated by qRT-PCR." (PMID 30459528, 2018).
cancer (continued). "The negative regulation of this pathway by the short isoform of TEAD4 suggests that TEAD4-S may repress cancer cell proliferation." (PMID 27291620, 2016). "In addition, RAD21 expression level was negatively correlated with the majority of ISGs that were identified as direct targets of RAD21 and TEAD4, a relationship that was also observed in an analysis of RNA-Seq data from 1,377 human cancer cell lines (Cancer Cell Line Encyclopedia)." (PMID 36201246, 2022). "As a molecular superglue for TEAD4, GLUP was shown to efficiently induce cancer cell death even in a cellular context with abundant glucose supply, yielding a strong antitumor effect in multiple mouse models including PDX." (PMID 39358623, 2024). "Among the cancers with a high TEAD expression, the expression of TEAD4 displayed the highest correlation with the poor prognosis of clear cell renal cell carcinoma (ccRCC)." (PMID 38607003, 2024). "TEAD4 is a DNA anchored protein of the Hippo-regulated YAP transcriptional complex, and it can promote tumorigenesis by regulating cancer stemness, metastasis and drug resistance." (PMID 37309005, 2023). "Here, we demonstrate a relevant oncogenic role of the TEAD4 transcription factor in cancer, which correlates with the oncogenic role of lnc-uc.147—described in BC and herein in liver—suggesting that the overexpression of lnc-uc.147 could be induced by the TEAD4 transcription factor." (PMID 36830634, 2023). "This revealed peaks for TEAD1 and TEAD4 on both KISS1 and CXCL8 promotors, suggesting that within cancer cells, TEAD transcription factors facilitate the expression of genes both up‐ and down‐regulated on NF2 loss." (PMID 36740402, 2023). "This suggests that global metabolism and epigenetics can be controlled by L-arginine in cancer cells via different sensing systems, such as CASTOR1, SLC38A9, and possibly TEAD4." (PMID 36982390, 2023). "CA3 treatment (1 μM; 48 h) in PC cells reduced the protein expression levels of PAF1, YAP1, TEAD4, CD133 (cancer stem cell marker), and SOX9 (pancreatic ductal marker)." (PMID 36180487, 2022). "Both genes are key components of the mammalian EMT/cancer-related Hippo pathway, being YAP1 a major transcriptional regulator and TEAD4 its essential binding partner in gene transcription regulation." (PMID 35500936, 2022). "TEAD4 interacts with KLF5 (Kruppel Like Factor 5) to suppress CDK inhibitor p27 expression, resulting in the cancer cell growth." (PMID 35602596, 2022). "Of note is a recent study of ccRCC TCGA datasets analysis, which reveals that TEAD4, compared to other three TEAD members, shows the most significant correlation with ccRCC malignancy and cancer progression." (PMID 35602596, 2022). "TEAD4 has been reported to be a protumor factor in LUAD, including its functions in promoting cancer cell proliferation, migration, and therapy resistance." (PMID 35600867, 2022). "An additional direct target of YAP/TEAD4 is a nucleotide sugar transporter, SLC35B4, which plays a key role in cancer metabolism and cancer cell proliferation." (PMID 35602596, 2022). "TEAD4, a critical member of the TEA domain (TEAD) family, has been identified as an oncogenic regulator in many cancers, including GC." (PMID 31924214, 2020). "Recently, sites occupied by Tead factors driving motility in cancer cells were identified and showed not only enrichment in AP1 motifs, but also many of the motifs that we found enriched at Tead4 sites in C2C12 cells." (PMID 28178271, 2017). "TEF3-1 (transcriptional enhancer factor 3 isoform 1), also known as TEAD4 (TEA domain family member 4), was recently revealed as an oncogenic character in cancer development." (PMID 26885617, 2016). "Our study provided TEAD4 LLPS as an example of an artificial induction of the formation of cell-growth-limiting condensates, opening a new perspective to elicit a biomolecular-condensate-based antitumor effect for therapeutic intervention of cancer." (PMID 39358623, 2024).
cancer (continued). "Through comparing the expression levels of TEAD4 in cancer versus normal tissue in both the ONCOMINE database and GEPIA dataset, we suggested that TEAD4 may participate in tumorigenesis in GC." (PMID 35739490, 2022). "The TEAD4/AP-1/SRC complex modulates a set of genes, including DOCKs (Dedicator of cytokinesis), CDH2 (Cadherin 2), and MACF1(Microtubule Actin Crosslinking Factor 1), to regulate cancer metastasis." (PMID 35602596, 2022). "For instance, TEAD4 might act as a putative oncogenic gene by enhancing the proliferation, migration, and invasion of HNSCC cancer cells." (PMID 34257533, 2021). "The CCND1 involved in cell cycle progression; TEAD4, a transcription factor in the Hippo signaling pathway; and EIF4EBP1, the translational regulator in PI3K/Akt/mTOR signaling, have been found to be significantly deregulated in several cancers." (PMID 32908901, 2020). "More interestingly, TEAD4 alone was able to transform MCF10A cells with efficiency comparable with that of TAZ, which raised the possibility that TEAD4 itself may act as an oncogene during cancer development." (PMID 26805820, 2016). "Induction of UNC5-family and NTN1 in YAPoff cancers depended on YAP/TEAD-binding as YAPS94A, which cannot bind TEADs, failed to induce UNC5B, and a TEAD4(DBD)-VP64 fusion mimicked the effects of YAP." (PMID 39172021, 2024).
cardiovascular disease (2 papers, 2014 to 2021). "In conclusion, TEAD2, TEAD4 and ZIC3 can increase the efficiency of reprogramming human urine cells into iPSCs, and provides a new stem cell sources for the clinical application and modeling of cardiovascular disease." (PMID 34448118, 2021).
infection (2 papers, 2022 to 2023). The state of being infected such as from the introduction of a foreign agent such as serum, vaccine, antigenic substance or organism. "Critically, targets of transcription factors known to regulate inflammation (IRF1, STAT1, STAT3) and fibrosis (SMAD2/3, EGR1, TEAD4, YAP1) appeared to be highly induced in the host, consistent with prior reports of infection-dependent induction of pro-inflammatory and pro-fibrotic gene expression." (PMID 36923592, 2023).
metabolic disease (1 paper, 2016). A congenital disorder (due to inherited enzyme abnormality) or acquired (due to failure of a metabolically important organ) disorder resulting from an abnormal metabolic process. "Moreover, the TEAD4 gene plays an important role in the gene-gene network that is involved in developmental disorders and metabolic disease." (PMID 28119630, 2016).
prostate (1 paper, 2021). "Finally, to analyze the clinical relevance of TEAD4 in prostate carcinogenesis, the OncomineTM Platform (Thermo Fisher, Ann Arbor, MI) was used for analysis and visualization." (PMID 33893278, 2021). "In addition, YAP1 expression is not positively correlated with TEAD4, supporting a YAP1-independent function of TEAD4 in prostate carcinogenesis." (PMID 33893278, 2021).
TEAD4 also shares sentences with these, for which no sentence is quoted: hepatocellular carcinoma (7 papers); head neck squamous cell carcinoma (4); cardiac hypertrophy (2); Cerebral ischemia (2); atypical teratoid rhabdoid tumor (1); cerebral edema (1); cholangiocarcinoma (1); congenital myasthenic syndrome (1); COVID-19 (1); cyst (1); digestive system tumours (1); dysplasia (1); esophageal adenocarcinoma (1); gastric intestinal type adenocarcinoma (1); gastric tumor (1); gastrointestinal carcinoma (1); invasive breast carcinoma (1); ischemic disease (1); keloid (1); liver diseases (1); myelogenous leukemia (1); nasopharyngeal carcinoma (1); oral cancers (1); pancreatic ductal adenocarcinoma (1); preeclampsia (1); pulmonary hypertension (1); renal clear cell carcinoma (1); serous ovarian carcinoma (1); small cell lung carcinoma (1); vasculopathy (1).
A further 1 disease shares a sentence with TEAD4 in 1 paper.